PDE6B (phosphodiesterase 6B)
Description:
Catalytic beta subunit of the rod-specific cGMP phosphodiesterase (PDE6) complex, which hydrolyzes 3',5'-cyclic GMP in the phototransduction cascade. The PDE6 holoenzyme consists of two catalytic subunits (PDE6A and PDE6B) and two inhibitory gamma subunits (PDE6G). Light-activated GNAT1 relieves gamma subunit-mediated inhibition, enabling the catalytic subunits to hydrolyze cGMP and thereby mediate visual signal transduction and amplification. Decreased cytosolic cGMP levels result in closure of cGMP-gated cation channels at the plasma membrane, leading to rod photoreceptor hyperpolarization (Probable). Involved in retinal circadian rhythm photoentrainment via modulation of UVA and orange light-induced phase-shift of the retina clock (By similarity).
Synonyms: PDEB; CSNB3; rd1; RP40; CSNBAD2; GMP-PDEbeta
Tractability: Small molecule: an approved drug acts on it; a high-quality ligand is known; it belongs to a druggable protein family. Antibody: its Gene Ontology location is reachable by antibodies, with high confidence. PROTAC: ubiquitination databases record sites on it; a small molecule that binds it is known.
Gene: Protein-coding gene on chromosome 4 (625,573 to 670,782, forward strand). Ensembl gene ENSG00000133256.
Subcellular location: Photoreceptor outer segment membrane; Membrane
Subcellular location (Human Protein Atlas): Basal body; Cytosol; Vesicles
Pathways (Reactome):
Sensory Perception: Activation of the phototransduction cascade; Inactivation, recovery and regulation of the phototransduction cascade
Signal Transduction: Ca2+ pathway
Gene Ontology:
Molecular function: 3',5'-cyclic-GMP phosphodiesterase activity; 3',5'-cyclic-AMP phosphodiesterase activity; 3',5'-cyclic-nucleotide phosphodiesterase activity; phosphoric diester hydrolase activity
Biological process: visual perception; entrainment of circadian clock by photoperiod; negative regulation of cAMP/PKA signal transduction; phototransduction, visible light; retina development in camera-type eye; transducin-mediated opsin signaling pathway; retinal cell apoptotic process; signal transduction
Cellular component: rod photoreceptor disc membrane; photoreceptor disc membrane; photoreceptor outer segment membrane; plasma membrane; membrane; photoreceptor outer segment
Genetic constraint (gnomAD): Loss-of-function variants: 76 observed, 74.31 expected, observed/expected ratio (o/e) 1.02, 90% interval 0.85 to 1.24. The upper end of that interval is the gene's LOEUF score, 1.24, which puts it in group 5 of 6, group 1 being the genes least tolerant of losing a copy. Missense variants: 929 observed, 921.88 expected, observed/expected ratio (o/e) 1.01, 90% interval 0.95 to 1.06. Synonymous variants: 372 observed, 374.1 expected, observed/expected ratio (o/e) 0.99, 90% interval 0.91 to 1.08.
Gene-disease validity (ClinGen):
ClinGen rates the evidence that PDE6B causes each of these diseases.
inherited retinal dystrophy (autosomal recessive): Definitive. An instance of retinal degeneration that is caused by an inherited modification of the individual's genome.
Homologues: Orthologues: macaque PDE6B (96% identical), mouse Pde6b (93% identical), rat Pde6b (93% identical), pig PDE6B (92% identical), dog PDE6B (92% identical), guinea pig PDE6B (92% identical), tropical clawed frog pde6b (81% identical), zebrafish pde6b (76% identical), zebrafish pde6a (72% identical), Drosophila melanogaster Pde11 (29% identical), Drosophila melanogaster Pde8 (14% identical), Caenorhabditis elegans pde-3 (12% identical), and 1 more. Paralogues in human: PDE6A (72% identical), PDE6C (64% identical), PDE11A (31% identical), PDE5A (29% identical), PDE2A (25% identical), PDE10A (22% identical), PDE4A (17% identical), PDE4D (17% identical), PDE3A (16% identical), PDE4C (16% identical), PDE4B (16% identical), PDE1C (15% identical), and 8 more.
Diseases named in the same sentence as PDE6B in open-access papers:
PDE6B is named in the same sentence as 67 diseases in open-access papers, as found by Europe PMC text mining. Sharing a sentence is not in itself a finding about the gene and the disease. The quoted sentences say what the papers report.
retinal degeneration (225 papers, 2007 to 2026). Degeneration of the retina. "This study demonstrates proof of concept for the precise correction of the Pde6b-L659P mutation causing retinal degeneration using BE, PE, and CE tools." (PMID 40607323, 2025). "The most widely used mouse model for retinitis pigmentosa has the retinal degeneration 1 (rd1) mutation in the Pde6b gene, which elicits rapid retinal degeneration and vision loss." (PMID 41380951, 2025). "Here, we aim to evaluate the potential of BE, PE, and CE technologies in rescuing the retinal degeneration-causing Pde6b (c.1976T>C, p.L659P) mutation." (PMID 40607323, 2025). "Of the five IRD genes with significant effects, three (Aipl1, Pde6a, Pde6b) are associated with a recessive retinal degeneration in humans." (PMID 41282224, 2025). "The Pde6bnmf137 mice, carrying a missense mutation c.1976T>C, p.L659P (hereafter referred to as the Pde6b-L659P mutation) in the Pde6b gene, exhibit severe photoreceptor degeneration and serve as a valuable model for studying and treating retinal degeneration." (PMID 40607323, 2025). "Here, we selected a retinal degeneration-associated Pde6b (c.1976T>C, p.L659P) mutation to perform a parallel evaluation of the BE, PE, and CE systems." (PMID 40607323, 2025). "Genetic analysis of rd10 mice has shown that a missense mutation in exon 13 of Pde6b disrupts rod photoreceptor function, leading to retinal degeneration." (PMID 40986557, 2025). "For instance, in the context of retinal degeneration, point mutations in genes such as Pde6b can trigger the progressive degeneration of photoreceptor cells, ultimately resulting in vision loss." (PMID 40607323, 2025). "Rd10 mice carry a spontaneous missense mutation in the Pde6b gene, which encodes the cGMP phosphodiesterase 6B, causing a later onset and slower progression of retinal degeneration that resembles RP in humans." (PMID 40869487, 2025). "Various mouse models have been used to further study retinal degeneration, including the rd10 mouse model, which encodes a missense point mutation in Pde6b (cGMP phosphodiesterase 6B; rod receptor; beta polypeptide)." (PMID 38248341, 2024). "It is characterized by early onset, rapid retinal degeneration due to a mutation in the rod-photoreceptor-specific Pde6b gene." (PMID 38303059, 2024). "The rd1 mouse model (pde6b gene mutation) has been well-characterized and widely used for retinal degeneration; it is used most commonly in retinitis pigmentosa since it leads to degeneration of rod photoreceptors." (PMID 39010943, 2024). "The well-studied mouse rd1 model, caused by the PDE6B-Y347X mutation, exhibits rapid retinal degeneration due to the extensive death of rods." (PMID 38137394, 2023). "RGCs in the rd1 mouse, the oldest and most widely studied animal model of retinal degeneration, become hyperactive after photoreceptor death caused by a mutation in the Pde6b gene." (PMID 37039777, 2023). "The PDE6B-T592I point mutation in the r28 mutant mice causes recessive and light-dependent retinal degeneration." (PMID 38137394, 2023). "The mutation in rd1 mice results in severe and early retinal degeneration, which is due to the insertion of a murine virus that introduces a nonsense mutation in exon 7 of the gene that encodes for phosphodiesterase 6β (PDE6β)." (PMID 37759678, 2023). "PDE6B gene mutations cause the death of rod photoreceptors, named as hereditary retinitis pigmentosa (RP) in humans and retinal degeneration (RD) in rodents." (PMID 38137394, 2023). "The rd10 phenotype carries a missense mutation (p.R560C, c.C1678T) in exon 13 of the pde6b gene and is another model of recessive retinal degeneration." (PMID 38139011, 2023). "Here, we report a new RD model, identified from a phenotypic screen of N-ethyl-N-nitrosourea (ENU)-induced mutant mice, which displays retinal degeneration caused by a point mutation in the Pde6b gene that results in PDE6B-T592I mutant protein." (PMID 38137394, 2023).
retinal degeneration (continued). "The rd1 is a fast progressive retinal degeneration model, due to a mutation in the gene for phosphodiesterase 6B (PDE6B), that causes the accumulation of the photoreceptor cGMP, and thus the activation of the cGMP-PKG system." (PMID 35883586, 2022). "Mice harboring the loss-of-function mutant of PDE6β (termed rd1 mouse) showed marked cGMP accumulation and subsequent severe retinal degeneration." (PMID 35452679, 2022). "Commonly used is the rd1 mouse model, due to the rapid rod-cone degeneration phenotype it displays resulting from a Pde6b nonsense mutation emulating late-stage retinal degeneration." (PMID 36710928, 2022). "Since the accumulated cGMP-dependent increase in calcium ion influx triggers retinal degeneration in rd1 mice, the underlying mechanisms of retinal degeneration in Lpcat1 KO mice differ from those in PDE6β mutated mice (rd1)." (PMID 35452679, 2022). "Retinal degeneration in inbred strains has been shown to be caused by a stop codon allele (Tyr347X) within Pde6b." (PMID 34589118, 2021). "To facilitate survival of transplanted human cells in the murine retina, we crossed the rd1 model of rapid retinal degeneration (caused by a mutation in PDE6β) with the immunocompromised Foxn1nu line." (PMID 33882303, 2021). "More importantly, using a natural occurring retinal degeneration model caused by a nonsense mutation of Phosphodiesterase 6b gene (Pde6bmut), we confirmed that MSCT and EXOT prevented photoreceptor loss and protected long-term retinal function." (PMID 33082517, 2021). "We further applied a genetic mouse retinal degeneration model caused by a nonsense mutation of Phosphodiesterase 6b gene (Pde6bmut), as previously established to mimick RP, and treated the mice with MSCs and exosomes at 2-week old." (PMID 33082517, 2021). "We adopted a breeding scheme where the Pde6b gene, which is associated to retinal degeneration, was bred out of the genetic background of the 5xFAD transgenic mice." (PMID 33597019, 2021). "The Rd10 mouse is another retinal degeneration model of PDE6β deficiency, as the Rd1, but the mutation is different." (PMID 34502238, 2021). "Here, we used a patient-derived RO model to demonstrate how the PDE6B mutation causes retinal degeneration in RP." (PMID 32211407, 2020). "The rd10 mouse offers an alternative slower model of retinal degeneration but also results from a mutation in Pde6b, although in this case it is a missense mutation that enables partial activity of Pde6b." (PMID 33262683, 2020). "For example, many researchers have used the rd1 mouse with a mutation in the Pde6b gene since it is the first strain of mouse identified with a retinal degeneration." (PMID 32466300, 2020). "Animal models like the retinal degeneration 1 (rd1) and the rd10 mouse, which harbor a mutated Pde6b gene, have advanced the understanding of the cellular processes underlying retinal degeneration." (PMID 30842506, 2019). "RP mouse models of early onset retinal degeneration produced by a mutation in the Pde6b gene showed changes in the postsynaptic cells of the rod and cone photoreceptors in the retina." (PMID 31117272, 2019). "The phenotype of the loss of ONL was reminiscent of that seen in mouse strains with early retinal degeneration mutations i.e. those targeting the Pde6b gene." (PMID 29969487, 2018). "The rd10 mouse model of RP harbors a mutation in phosphodiesterase-6b (pde6b) and is widely used to study retinal degeneration and investigate potential therapeutics for RP." (PMID 28216676, 2017). "The potential limitations of this model are that it mimics only a single aspect of retinal degeneration (i.e. RP caused by PDE6B gene mutation)." (PMID 28258056, 2017). "It shows an early onset of retinal degeneration starting from weaning age due to a xenotropic murine leukemia viral insert (Xmv28) in the first intron of Pde6b and a non specific mutation in the 349th base pair of exon 7 of the Pde6b gene." (PMID 28258056, 2017).
retinal degeneration (continued). "This was because the mice were partially in a Black Swiss background, which carried a fast-acting allele of retinal degeneration (Pde6b-/-, Rd1)." (PMID 26949938, 2016). "It carries a naturally occurring nonsense mutation in the photoreceptor cGMP phosphodiesterase 6b (Pde6b) gene and is the oldest and most widely used animal model for studying the mechanisms of retinal degeneration." (PMID 25613321, 2015). "These were used to identify the progressive loss of neurons in the FVB/N mouse, a model of early onset retinal degeneration produced by a mutation in the pde6b gene." (PMID 26091175, 2015). "The rd1 mouse with a mutation in the Pde6b gene was the first strain of mice identified with a retinal degeneration." (PMID 25613321, 2015). "This strain carries the retinal degeneration (rd) mutation of the Pde6b (phosphodiesterase 6B, cGMP, rod receptor, beta polypeptide) gene, with consequent vision loss." (PMID 23441200, 2013). "The retinal degeneration 10 (rd10) mouse is a model of autosomal-recessive RP caused by a point mutation of the Pde6b gene." (PMID 22615940, 2012). "The inbred line that the Dscam3J allele arose on carries the recessive retinal degeneration allele of Pde6b, rd1." (PMID 23300735, 2012). "Rd1 mice show early onset and rapid retinal degeneration caused by mutations in Pde6b." (PMID 40347492, 2025). "The progressive retinal pathologies in FUN025 mice differ from rapid retinal degeneration observed in mice with mutations in phosphodiesterase 6B (Pde6b), rhodopsin (Rho), and other genes linked with inherited retinal diseases in humans that is complete by two to three weeks of age." (PMID 38576540, 2024). "The ARPE-19 cell line used in this study was isolated from primary human RPE cells and is commonly used as an in vitro model of RD; rd10 mice have a missense mutation in phosphodiesterase 6B, and these mice have retinal degeneration that complete at 60 days of age." (PMID 36644575, 2023). "Sixth, experimental overexpression of KITL also partially protects against photoreceptor cell loss in Kit+/+ mice harboring mutations in Pde6b, the mouse homolog of the human RP gene, whose mutations are associated with retinal degeneration in both mice and humans." (PMID 32242818, 2020). "Retinal degeneration in the rd10 mouse is caused by a point mutation on exon 13 in the Pde6b gene." (PMID 30042417, 2018). "In addition, a young patient with pde6b and myo7a gene mutations (underlying USH1B) presented earlier and more sever retinal degeneration than his older siblings with a homozygous pde6b mutation." (PMID 27186975, 2016). "This is consistent with former reports and might rely on presence of mutations in the Pde6b or deletion in the CP49 gene (implicated in retinal degeneration or establishing of lens fiber network) in this strain." (PMID 27377996, 2016). "• C3H/HeJ, a strain harboring the original rd1 retinal degeneration mutation in the Pde6b gene." (PMID 19727342, 2009). "Therefore, we considered the human SP4 gene a good candidate for the site of missense mutations causing retinal degeneration, given its involvement in the transcription of several photoreceptor genes including PDE6B and the phenotype of the Sp4 knockout mouse." (PMID 17356515, 2007). "Interestingly, variants in rhodopsin, Pde6a, Pde6b, Prph2 and Rom1 are associated with inherited retinal degeneration in both humans and mice, and their downregulation may underlie the retinal degenerative phenotype observed in Hbs1ltm1a/tm1a mice." (PMID 38966981, 2024). "Rd1 mouse is an animal model of rapid retinal photoreceptor degeneration; the phenotype is mainly caused by mutations in the β subunit of rod cGMP-phosphodiesterase (PDE6β), which results in cGMP accumulation in the retina, eventually causing early onset severe retinal degeneration." (PMID 31080404, 2019).
retinal degeneration (continued). "As previously reported in other rodent models of retinal degeneration, disease induced activation of retinal microglia can be detected as early as post-natal day 14 in Pde6b-null rats." (PMID 41250236, 2025). "It has been shown recently by a multi-omic study that early metabolic imbalance and mitochondrial stress in neonatal photoreceptors lead to cell death in the Pde6b rd1 mouse model of retinal degeneration." (PMID 37979052, 2023). "Because of the apparent retinal degeneration phenotype, we sequenced the Pde6b gene using the cDNA made from the r28/r28 mutant retina." (PMID 38137394, 2023). "We compare this Pde6b-KO mouse model to the rd1 mouse model to gain insights into the progression of retinal degeneration." (PMID 38139011, 2023). "Here, we successfully delivered in vitro-derived human photoreceptor precursor cells (PRPCs; also known as immature photoreceptors) to the subretinal space of seven normal and three rcd1/PDE6B mutant dogs with advanced inherited retinal degeneration." (PMID 35905738, 2022). "In this study, we describe the basic phenotype of a novel LE Pde6b KO rat model simulating human retinal degeneration." (PMID 36213678, 2022). "We generated a Pde6b knockout rat model as a retinal degeneration model that typically shows generalized retinal cell damage and reduced retinal thickness 3 weeks after postnatal development." (PMID 33828232, 2021). "HBCGM analysis identified a haplotype block within phosphodiesterase 6b (Pde6b) that completely correlated with the pattern of retinal degeneration in both male and female mice (pHBCGM = 0)." (PMID 34589118, 2021). "For contrasting rod/cone degenerations, in this study we compared two forms of inherited retinal degeneration in mice Mus Musculus, the C3H/HeJ-Pde6brd1 mouse (rd1) and the C3A.Cg-Pde6b+Prph2Rd2/J mouse (Rd2)." (PMID 33493166, 2021). "The rd1 mouse, representing the most severe and early form of human retinal degeneration, harbors a mutant Pde6b gene mapped on chromosome 5." (PMID 32123325, 2021). "Augmented expression of HSP70 in RHOT17M mice, in which mutant rhodopsin is misfolded, marginally improved photoreceptor survival, whereas elevated HSP70 led to more severe retinal degeneration in rd10 mutants that produce a partially functional PDE6B." (PMID 33107904, 2020). "Mice homozygous for the rd10 mutation, a missense mutation in the exon 13 of the beta subunit of the rod phosphodiesterase gene Pde6b, show retinal degeneration at 1 month of age." (PMID 32362442, 2020). "In the FVB strain, the retinal degeneration allele is called 'rd1' not 'd1', and the gene is 'Pde6b' not 'Pde6br'." (PMID 39111836, 2024). "As rd1 mice show similar phenotypes to those of Lpcat1 KO, early-onset, and light-independent retinal degeneration, we assessed whether the altered membrane lipid composition in Lpcat1 KO photoreceptor cells leads to PDE6β dysfunction." (PMID 35452679, 2022). "We believe that the LE Pde6b KO model may be used effectively for preclinical translational research to further study retinal degeneration." (PMID 36213678, 2022). "Here, we developed and explored the Pde6b-knockout LE rat model that may enhance the utility of these animal models in preclinical research on retinal degeneration." (PMID 36213678, 2022). "In this study, we evaluated the long-term effects of hiPSC-derived RPE and photoreceptor cell transplantation in Pde6b knockout rats to study RP; cells were injected into the subretinal space of the right eyes of rats before the appearance of signs of retinal degeneration at 2–3 weeks of age." (PMID 33828232, 2021). "We can now confirm that the absence of SP-A and SP-D proteins in Sftpa1tm1Kor/J and Sftpd gene targeted mice, do not lead to early retinal degeneration but is a result of the Pde6brd1 mutation on the Pde6b gene." (PMID 29969487, 2018).